IL6 (interleukin 6)
Diseases named in the same sentence as IL6 in open-access papers (continued):
Sharing a sentence is not in itself a finding about the gene and the disease.
endothelial dysfunction (continued). "In the PVAT, at the earliest time point assessed i.e., 6 h.p.i and prior to endothelial dysfunction there was a significant but small elevation in CD69 and IFN-γ but no change in TNF-α, IL-6, or NOX2." (PMID 35930608, 2022). "We have not evaluated various indicators related to inflammation or endothelial dysfunction, such as TNF-a and IL-6." (PMID 32433661, 2020). "Biomarkers of endothelial dysfunction and low-grade inflammation were not modified (CRP, serum amyloid A, IL-6, IL-8, TNF-α, and soluble intercellular adhesion molecule-1) and neither was FMD." (PMID 31068933, 2019). "IL-6, rheumatoid factor titre and low GFR predicted endothelial dysfunction, as assessed by biomarkers, independent of traditional cardiovascular risk factor in the 74 RA patients." (PMID 15899050, 2005). "Even in the absence of bacteremia, cytokine release (IL-6, TNF-α, IL-1β) may induce endothelial dysfunction, increased capillary permeability, and myocardial edema, which could suggest worsening of myocardial involvement by SIRS." (PMID 41466908, 2025).
type 2 diabetes (868 papers, 2004 to 2026). "Elevated levels of proinflammatory cytokines in obese individuals, such as interleukin (IL)-1beta and IL-6, increase the risk of developing type 2 diabetes, and there is evidence that these low levels of circulating cytokines can lead to islet dysfunction." (PMID 41745595, 2026). "Some studies report a positive association between IL‐6 concentration, insulin resistance, atherosclerosis, Type 2 diabetes, and cardiovascular disease." (PMID 41559866, 2026). "For instance, clinical trials have demonstrated that a BW-based diet can prevent the increase in interleukin (IL)-6 levels caused by type 2 diabetes and the tumor necrosis factor (TNF)-α, which are key inflammation markers." (PMID 39861525, 2025). "High sugar intake and physical activity status significantly influence IL-6 levels, although their associations with type 2 diabetes risk remain equivocal." (PMID 41190158, 2025). "In the UK-based Edinburgh Type 2 Diabetes Study, higher baseline levels of IL-6 were significantly associated with a decline in abstract reasoning and executive function within a 10-year follow-up period." (PMID 40606939, 2025). "Serum BDNF levels are markedly reduced in type 2 diabetic patients with nephropathy and correlate with deficiencies in vitamins D, B12, folate, and zinc, as well as elevated IL-6 and IL-12." (PMID 41142318, 2025). "IL-1β, a major pro-inflammatory cytokine, is critically involved in INS signaling alterations; in obese individuals, high IL-1β and IL-6 circulating levels represent an important independent risk for developing type 2 diabetes." (PMID 40940769, 2025). "For adipose tissues, IL‐6 can stimulate visceral fatty lipolysis, and the IL‐6 autoantibody has been implicated in the pathogenesis of type 2 diabetes." (PMID 38988494, 2024). "The meta-analysis found a significant association between elevated IL-6 levels and an increased risk of type 2 diabetes, with a relative risk (RR) of 1.31." (PMID 39404426, 2024). "Type 2 diabetes is a proinflammatory condition, characterized by higher levels of IL-6, IL-8, and TNF-α, which are associated with worse clinical outcomes and are highest in the presence of comorbidities." (PMID 37934800, 2024). "It has been shown that in patients with the G/G genotype within the rs1800795 polymorphism (IL6), the chance of developing type 2 diabetes is several times lower compared to patients with the G/C and C/C genotypes." (PMID 38250713, 2024). "The concentration of IL-1β is increased in OB humans, with the combination of elevated IL-1β and IL-6 increasing the risk of both type II diabetes and metabolic syndrome." (PMID 39328456, 2024). "The main finding of this prospective proof-of-concept study is that three months of empagliflozin in patients with HFrEF and diabetes mellitus type II is associated with a reduction in soluble interleukin-6 levels." (PMID 37445494, 2023). "IL-6 is significantly elevated in both type 1 and type 2 diabetes and is a proven risk factor and independent predictor of type 2 diabetes." (PMID 36768679, 2023). "In analogy to our findings with empagloflozin, canagliflozin reduced IL6 concentrations in patients with type 2 diabetes at high cardiovascular risk." (PMID 37445494, 2023). "Multiple studies indicated that a pro-inflammatory state is a component of T2D with dyslipidemia and a correlation between high Interleukin 6 (IL-6) levels and subjects with type 2 diabetes and dyslipidemia risk factors has been observed." (PMID 37542207, 2023). "For example, high concentration of IL-6 have been reported to be an independent risk factor for type II diabetes and cardiovascular disease." (PMID 36647426, 2023). "Elevated levels of fasting plasma IL6 has been linked with increased risk of cardiovascular disease and type 2 diabetes in postmenopausal women." (PMID 36364884, 2022).
type 2 diabetes (continued). "Higher baseline levels of inflammatory markers, including plasma IL-6, fibrinogen and C-reactive protein, were associated with subsequent cognitive decline in older people with type 2 diabetes." (PMID 34932135, 2022). "Firstly, nut consumption has been reported to be associated with improved inflammatory status, including C-reactive protein, interleukin-6, and fibrinogen, and thus reduce risk of cardiovascular disease and type 2 diabetes." (PMID 36570151, 2022). "The fasting IL6 levels in this study suggests that some of the study participants are at a higher risk for developing type 2 diabetes." (PMID 36364884, 2022). "IL-6 is traditionally considered a regulator of acute-phase responses, and its levels are strongly associated with cardiovascular disease, type 2 diabetes, and liver functional decline." (PMID 35889040, 2022). "To examine if IL-6 correlates with cardiovascular risk, we considered hypertension, type 2 diabetes, smoking, male gender, age above 60 years, and the presence of CHD as isolated risk factors and correlated with IL-6." (PMID 36028849, 2022). "Reduced nerve conduction velocity has been associated with increased IL6 in patients with type 1 and recently diagnosed type 2 diabetes and early neuropathy." (PMID 35329958, 2022). "Testosterone replacement therapy to testosterone-deficient men undergoing type 2 diabetes decreases the synthesis of the proinflammatory cytokines IL-1β, IL-6 and TNF-α in antigen-presenting cells." (PMID 36551196, 2022). "In a study of type 2 diabetes, an increase in IL-6 associated with weight gain was shown to be related to an increased risk of CKD." (PMID 34535101, 2021). "Among type 2 diabetics, sensorimotor neuropathy was associated with IL6 and adiponectin levels in an age and gender analysis." (PMID 33810048, 2021). "IL-6 also stimulates low-grade inflammatory processes involved in the pathogenesis causing type 2 diabetes." (PMID 33868439, 2021). "Observational studies have shown that IL-6 is a risk factor for type 2 diabetes but its role in beta cell survival in type 1 diabetes is small." (PMID 33535417, 2021). "The correlation between IL6 polymorphisms and type 2 diabetes susceptibility has been described by many researchers but remains controversial." (PMID 32961860, 2020). "Obesity, possibly hypertension, type 2 diabetes (T2D) and ageing all represent risk factors for severe COVID-19 associated with cytokine storm and IL-6, endothelial damage in different organs and lung damage." (PMID 33292691, 2020). "IL–6 also stimulates low-grade inflammatory processes and has been proposed to be involved in the pathogenesis causing type 2 diabetes." (PMID 32349742, 2020). "Numerous studies have provided clear evidence that IL-6 C-174G single-nucleotide polymorphism was a risk factor in Type 2 diabetes and contributed to higher serum interleukin-6 level among the participants." (PMID 33016995, 2020). "Elevated levels of IL-6 and IL-1β in adipose tissue have been reported to contribute to the risk of type 2 diabetes." (PMID 32019160, 2020). "In the Edinburgh Type 2 Diabetes Study, levels of three pro-inflammatory markers (IL-6, TNF-α and CRP) was associated with worse cognitive performance in 1,066 older adults with T2DM, many of whom had established T2DM-related complications." (PMID 33424582, 2020). "Biomarkers of pro-inflammatory cytokines, including TNF-α and IL-6, are elevated in type-2 diabetes associated with the acceleration of atherosclerosis progression." (PMID 32957558, 2020). "In individuals with type 2 diabetes, increased IL-6 levels have been suspected as a cause of lowered GSH levels." (PMID 31024337, 2019). "In obese and type 2 diabetics patients, up-regulation of IL-6 levels were associated with elevated blood sugar levels, low sugar tolerance and decreased sensitivity to insulin." (PMID 30463907, 2019). "It was reported that IL-6 was associated with reduced glomerular filtration rate (GFR) in type 2 diabetic patients." (PMID 29682583, 2018).
type 2 diabetes (continued). "Multiple studies have shown that associations of CRP and IL-6 with type 2 diabetes vary by race and ethnicity, sex, and body mass index." (PMID 28753646, 2017). "Recently, it was found that IL-6 gene 174G>C polymorphism is an independent risk factor for DN in Turkish and Greek type 2 diabetic mellitus patients." (PMID 28484449, 2017). "Numerous studies have also associated increased levels of IL-6 with the development of type 2 diabetes." (PMID 27843953, 2016). "Elevated levels of IL-6 were associated with higher incidence of type 2 diabetes, and animal studies also showed IL-6 to inhibit insulin secretion from islet cells following glucose stimulation." (PMID 26911440, 2016). "Previous studies conducted to assess variations in inflammatory markers associated with type 2 diabetes in urban populations have indicated a significant difference in the levels of interleukin 6 (IL-6) and tumour necrosis factor α (TNF-α)." (PMID 26391589, 2015). "Individuals with combined elevated plasma levels of IL-1β and IL-6 are at increased risk for developing type 2 diabetes, but even mild weight loss in obese patients resulted in a 45% decrease in serum IL-1β levels over a three-year study period." (PMID 25403235, 2014). "IL-1β together with IL-6 concentrations reportedly predicts risk for type 2 diabetes in humans better than either cytokine alone." (PMID 25309773, 2014). "An elevation in circulating levels of IL-1β together with IL-6 has been shown to increase the risk of type 2 diabetes." (PMID 24918199, 2014). "For example, increases of the pleiotropic cytokine interleukin-6 (IL-6) have been found to influence the onset and course of a wide spectrum of age-associated diseases including cardiovascular disease, arthritis, type 2 diabetes and certain cancers." (PMID 25285197, 2014). "We validated the upregulation of Il-6, the gene encoding IL-6, one of the several pro-inflammatory cytokines associated with IR and type 2 diabetes." (PMID 25073444, 2014). "Regarding type 2 diabetes, a meta-analysis of ten prospective studies with a total of 19,709 participants revealed a significant dose-response association of IL-6 levels with risk of type 2 diabetes (relative risk, [RR] 1.31, 95% CI 1.17–1.46)." (PMID 24988532, 2014). "It was showed that elevated concentrations of pro-inflammatory cytokines such as IL-6 and acute phase reactants such as C-reactive protein are in turn independent risk factors for the development of type 2 diabetes and CVD." (PMID 25266321, 2014). "IL6 is a marker of low-grade inflammation and has been suggested as a risk factor for type 2 diabetes and cardiovascular disease." (PMID 23923049, 2013). "Adipocytokines such as leptin and adiponectin or the proinflammatory cytokine interleukin-6 (IL-6) are affected by lifestyle habits and seem to play an important role for weight development, body composition and risk for type 2 diabetes." (PMID 24098730, 2013). "It is likely that oxidative stress is associated in type 2 diabetic patients with a systemic inflammatory status characterized by increased levels of cytokines as IL6 and TNF-α." (PMID 23383177, 2013). "A German group investigated the association between IL-6 and primary CV events in 1072 patients with type 2 diabetes during 5 years follow-up and found a significant association with adverse events." (PMID 23987834, 2013). "Multiple adjustments resulted in some attenuation of these estimates but the pattern of association persisted, apart from the association between IL-6 and type 2 diabetes incidence, which was mostly removed." (PMID 23843750, 2013). "As for the entire study group, we observed a significant association between CV diseases (R2=0.1; p=0.04), type 2 diabetes (R2=0.13; p=0.02) and plasma IL-6 as well as a trend for CV risk factors (R2=0.08; p=0.07)." (PMID 24244750, 2013).
type 2 diabetes (continued). "Both IL-1β and IL-6 are known to be regulated in this manner and have been implicated in the pathogenesis of IR and progression to overt type-2 diabetes." (PMID 23844177, 2013). "In the present study, in individuals with type 2 diabetes, we explored the association of these novel CV risk markers (pathological recovery phase, E/Em, IL-6 and activin A) with major CV events and mortality." (PMID 23987834, 2013). "For IL-6 production upon alum stimulation, CV risk factors (R2=0.06; p=0.02), type 2 diabetes (R2=0.04; p=0.048), CV diseases (R2=0.05; p=0.02), monocytes counts (R2=0.06; p=0.02) were significant predictive factors." (PMID 24244750, 2013). "Our study further indicates an association between IL-6 and CV events and all cause mortality in people with type 2 diabetes potentially giving prognostic information beyond traditional risk factors." (PMID 23987834, 2013). "Several in vitro, in vivo studies and clinical trials provide evidence that supports a causative role of IL-1β in the pathogenesis of type 2 diabetes, and elevation in circulating levels of IL-1β predicts type 2 diabetes when combined with serum IL-6 levels." (PMID 23843683, 2013). "Interleukin-6 (IL-6) has also been associated with cardiometabolic diseases; its concentrations were shown to be predictive of type 2 diabetes (T2D)." (PMID 23176569, 2012). "In sharp contrast, adipose production and secretion of IL-6 is chronically elevated in obese people and elevated plasma IL-6 is an independent risk factor for developing type 2 diabetes." (PMID 22761857, 2012). "Of the many cytokines examined in this context, IL-6 exhibits a strong association not only with cardiovascular mortality itself but also with cardiovascular risk factors like type 2 diabetes, hypertension and lipid abnormalities." (PMID 21935443, 2011). "For example, a common polymorphism in the IL-6 gene, -174G>C, has been found to be associated with risk for type 2 diabetes in the majority of population-based human studies." (PMID 21179199, 2010). "IL-6 plasma levels also correlate with the development of the metabolic syndrome and predict future risk for type 2 diabetes." (PMID 19936194, 2008). "Overproduction of IL-6, a pro-inflammatory cytokine, is associated with a spectrum of age-related conditions including cardiovascular disease, osteoporosis, arthritis, type 2 diabetes, certain cancers, periodontal disease, frailty, and functional decline." (PMID 17374166, 2007). "In addition, dry eye disease is highly prevalent among patients with type 2 diabetes and has been consistently linked to increased tear concentrations of proinflammatory cytokines such as IL-6, CXCL8, and TNF-α." (PMID 41030257, 2025). "Furthermore, the IL6 instrument showed associations with lower risk of type 2 diabetes and increases in high-density lipoprotein (HDL) particles." (PMID 40858837, 2025). "In addition, anthocyanins inhibit low‐grade chronic inflammation by inhibiting the inflammatory mediators TNF‐α, IL‐6, and NF‐κB signaling pathways implicated in the progression of type 2 diabetes." (PMID 40918166, 2025). "Augmented IL-6 concentrations have been correlated to a higher risk of developing type 2 diabetes." (PMID 40218888, 2025). "Elevated levels of IL-6 and IL-1β have been shown to increase the risk of type 2 diabetes." (PMID 38257186, 2024). "Interestingly, in a Caucasian population, the IL-6-597 G/A promoter polymorphism showed associations with type 2 diabetes." (PMID 38396821, 2024). "These combined results suggest that the dietary habit of consuming soft foods contributes to both the onset of type 2 diabetes and its associated muscle atrophy, which is due, at least in part, to an increase in IL-6 induced by elevated blood glucose or triglyceride, or both." (PMID 38561446, 2024).